KLF6 (KLF transcription factor 6)
Diseases named in the same sentence as KLF6 in open-access papers (continued):
Sharing a sentence is not in itself a finding about the gene and the disease.
acute kidney injury (4 papers, 2020 to 2023). Sudden and sustained deterioration of the kidney function characterized by decreased glomerular filtration rate, increased serum creatinine or oliguria. "Proximal tubular-specific knockdown of Krüppel-like factor 6 (KLF6), a transcription factor that is induced in the proximal tubule early in acute kidney injury and that suppresses BCAA catabolism, protected mice against acute renal injury and fibrosis." (PMID 35186675, 2022). "Moreover, overexpression of circMTO1 was found to attenuate acute kidney injury (AKI) by sponging miR-337 and regulating the expression of Kruppel like factor 6 (KLF6)." (PMID 34277605, 2021). "Krüppel-like factor 6 (KLF6) is a transcription factor that participate in various pathophysiological processes, but its contribution in ischemia acute kidney injury (AKI) is lacking so far." (PMID 32698645, 2020). "Regarding the kidney, recent studies showed that KLF2, KLF4, KLF5, KLF6, and KLF15 were distributed in glomeruli and renal tubules and played important roles in the occurrence and development of proteinuric glomerular diseases and acute kidney injury 28-32,53,54." (PMID 36632460, 2023).
asthma (4 papers, 2020 to 2025). "Perturbagens for 5 tissue types: The genetic perturbagen Kruppel-like factor 6 (KLF6) is negatively associated with asthma in airway epithelial cells, macrophages, distal airway fibroblasts, CD8+ peripheral blood lymphocytes and nasal epithelial cell transcriptomes." (PMID 32900903, 2020). "Association of KLF6 gene with lung function has been indicated from genomic data and from in vitro experiments which showed that blocking of KLF6 in vitro can decrease transforming growth factor β (TGF-β) production leading to airway remodeling and asthma." (PMID 32900903, 2020). "Drug (entinostat, BMS-345541) and genetic perturbagens (KLF6, BCL10, INFB1 and BAMBI) negatively connected to disease at multi-tissue level could potentially repurposed for treating asthma." (PMID 32900903, 2020).
Cirrhosis (4 papers, 2018 to 2024). A chronic disorder of the liver in which liver tissue becomes scarred and is partially replaced by regenerative nodules and fibrotic tissue resulting in loss of liver function. "Only the PNPLA3, TM6SF2, and KLF6 SNPs were then selected to constitute the genetic risk score, participating according to the model which best fitted with their association to the risk of NASH cirrhosis." (PMID 29732362, 2018). "In addition, liver samples from cirrhosis patients exhibited reduced miR-122 levels, while NEAT1 and Kruppel-like factor 6 (KLF6) increased." (PMID 30931332, 2019).
diabetic nephropathy (4 papers, 2020 to 2025). "In diabetic nephropathy, KLF6 downregulation in glomeruli and podocytes coincides with mitochondrial fragmentation, respiratory dysfunction, and oxidative stress, culminating in podocyte apoptosis." (PMID 40265156, 2025). "Similar mitochondrial morphological alterations following KLF6 deletion were subsequently evident in a diabetic nephropathy model, but the regulatory mechanisms remain poorly understood." (PMID 40265156, 2025). "Here, the authors show that podocyte KLF6 attenuates proximal tubule injury via ApoJ-CaMK1D signaling in a murine model of diabetic kidney disease." (PMID 39271683, 2024). "Two independent studies identified the TGFβ-KLF6 axis as playing a central role in driving renal and pulmonary fibrosis in the in-vitro and in-vivo models of diabetic nephropathy." (PMID 32998281, 2020). "The anti-inflammatory protein PPARγ was found to be one of the downstream targets of the TGFβ-KLF6 pathway during renal inflammation and the progression of diabetic nephropathy." (PMID 32998281, 2020).
Hepatic steatosis (4 papers, 2018 to 2024). Steatosis is a term used to denote lipid accumulation within hepatocytes. "In addition to its essential role in fetal liver development, KLF6 is involved in the pathogenesis of liver steatosis and fibrosis." (PMID 29942807, 2018). "Klf6 and Tgfb1 are upregulated during the progression of rat models of NASH, and hepatocyte-specific Klf6 deletion is protective against HFD-induced liver steatosis and insulin resistance, which suggests KLF6 contributes to NASH development." (PMID 29942807, 2018).
ischemia (4 papers, 2020 to 2023). A hypoperfusion of the BLOOD through an organ or tissue caused by a PATHOLOGIC CONSTRICTION or obstruction of its BLOOD VESSELS, or an absence of BLOOD CIRCULATION. "We found that the expression level of KLF6 was significantly suppressed in the OGD/R- treated brain vascular endothelial cells, indicating that KLF6 might be involved in the pathological mechanism underlying BBB disruption post-ischemia." (PMID 34605354, 2021). "In this study, KLF6 expression was significantly increased in vivo, in vitro, and in clinical specimens after hepatic ischemia-reperfusion, suggesting its role as a key regulator of hepatic I/R injury." (PMID 37391422, 2023). "In-line with these findings, the marked upregulation of KLF6 and TGFβ were also observed at the early phase of kidney ischemic reperfusion (I/R) injury, and KLF6 targeting impaired the apoptotic process following the ATP-induced ischemia." (PMID 32998281, 2020).
liposarcoma (4 papers, 2017 to 2022). A usually painless malignant tumor that arises from adipose tissue. "The overexpression of KLF6 partially induced phenotypic changes in dedifferentiated liposarcoma cells that contributed to the development of adipocytic differentiation." (PMID 33498189, 2021). "Kruppel-like factor 6 (KLF6) was decreased in dedifferentiated liposarcoma with increased H3K9me3 hypermethylation." (PMID 33498189, 2021). "Moreover, it was reported that KLF6 acts as a tumor suppressor in liposarcoma inhibiting cellular proliferation and invasion, and drive senescence and differentiation through the regulation of master regulators of adipogenesis." (PMID 31824948, 2019).
lung adenocarcinoma (4 papers, 2020 to 2025). A carcinoma that arises from the lung and is characterized by the presence of malignant glandular epithelial cells. "Trifluoperazine, a phenothiazine derivative, enhances FOXO1 nuclear retention and counters AKT-driven resistance to erlotinib by activating the KLF6/FOXO1 signaling pathway in lung adenocarcinoma." (PMID 40718442, 2025). "Trifluoperazine, in particular, enhances FOXO1 nuclear retention and reverses resistance mechanisms in lung adenocarcinoma by activating the KLF6/FOXO1 pathway." (PMID 40718442, 2025). "Finally, we show that AGT and HMGA1 mRNAs were upregulated while KLF6 mRNA was downregulated in human lung adenocarcinoma, as demonstrated by The Cancer Genome Atlas analysis." (PMID 33380422, 2021). "Furthermore, KLF6 downregulation was correlated with activated EGFR and phosphorylated AKT in patient-derived lung adenocarcinoma samples and decreased KLF6-induced resistance to erlotinib both in vitro and in vivo." (PMID 32552913, 2020).
multiple myeloma (4 papers, 2018 to 2025). "Up regulation of KLF6 has already been linked to increased susceptibility to BTZ of myeloma cells." (PMID 33972578, 2021). "Next, we further analyzed the regulatory activity of TOP5 TF of C0 IGLC3+ Myeloma cells, and we visualized the expression of KLF6, NR3C1, IRF7, YY1 and JUN in all cells and different tissue sources." (PMID 40406148, 2025). "Galectin-1 (LGALS1) release is a common feature of inflammatory cell death, including necroptosis, while KLF6 downregulation has been shown to rescue the death of bortezomib-resistant multiple myeloma cells." (PMID 37397499, 2023). "In the present study, we analyzed the expression of the wild type (WT) gene KLF6 and the oncogenic splice variant 1 (KLF6–SV1) at the mRNA level in subsets of T cells from CLL patients (n = 29), multiple myeloma patients (n = 6) and normal donors (n = 10)." (PMID 29432497, 2018). "We analyzed the regulatory activity of TOP5 TFs in C0 IGLC3+ Myeloma cells and found that KLF6 was actively regulated in MM, and IRF7 and NR3C1 might be active in MM." (PMID 40406148, 2025). "The results showed that KLF6, NR3C1, IRF7 and YY1 were all actively regulated in C0 IGLC3+ Myeloma Cells, C1 IGHA1+ Myeloma Cells, and JUN was actively regulated in C0 IGLC3+Myeloma Cells, C1 IGHA1+ Myeloma Cells and C3 IGHG4+ Myeloma Cells." (PMID 40406148, 2025).
non-alcoholic fatty liver disease (4 papers, 2013 to 2020). "KLF6 is a pro-fibrogenic transcription factors and associated with fibrosis in non-alcoholic fatty liver disease." (PMID 33101221, 2020). "KLF6 was implicated as a novel regulator of hepatic glucose and lipid metabolism in non-alcoholic fatty liver disease, characterized by dysregulated glucose homeostasis." (PMID 27902686, 2016). "KLF6-expression contributes to hepatic insulin resistance and the progression of non-alcoholic fatty liver disease (NAFLD) to non-alcoholic steatohepatitis (NASH) and NASH-cirrhosis." (PMID 28808340, 2017).
oral cancer (4 papers, 2018 to 2024). "Studies have shown that in oral cancer tissues, the expression of KLF6 is significantly reduced." (PMID 33955459, 2021). "KLF6 overexpression has been known to induce apoptosis and inhibit cell proliferation and migration in various cancer cells; one study showed the tumor suppressive function of KLF6 in oral cancer cells." (PMID 33244087, 2020).
psoriasis (4 papers, 2013 to 2023). An autoimmune condition characterized by red, well-delineated plaques with silvery scales that are usually on the extensor surfaces and scalp. "KLF6, which has been reported to strongly associate with T cell activation in psoriasis, was also found to be expressed at higher levels in CD1a-GAS reactive IL-22-producing T cells." (PMID 37267382, 2023). "Using weighted correlation analysis we identified SPATS2L and KLF6 coexpression networks, which were also significantly associated with psoriasis (p-value < 0.05)." (PMID 24267790, 2013). "This study has identified two new genes, SPATS2L and KLF6, strongly associated with T cell activation in psoriasis." (PMID 24267790, 2013). "Moreover, KLF6 strongly associated with T-cell activation in psoriasis, and KLF6 knockout mice showed a protected effect to against chemically induced colitis, suggesting a central role of myeloid KLF6 in pro-inflammatory activation in the setting of chronic intestinal inflammation." (PMID 32698645, 2020). "We have identified SPATS2L and KLF6 as the two genes most significantly overexpressed in activated T cells from psoriasis patients and we have validated this overexpression in an independent case-control cohort." (PMID 24267790, 2013). "After technical validation, we used an independent sample of patients and controls recruited from the same University Hospitals to validate the association of SPATS2L, KLF6 and SP140 genes with the activation of T cells in psoriasis." (PMID 24267790, 2013). "Using in vitro activated T cells from 8 patients and 8 controls we significantly validated the overexpression of SPATS2L (FC = 1.58, p-value = 0.0014) and KLF6 (FC = 1.23, p-value = 0.024) genes in psoriasis." (PMID 24267790, 2013). "Using an independent cohort of 8 patients and 8 healthy controls we validated the overexpression of SPATS2L (p-value =0.0009) and KLF6 (p-value =0.0012) genes in activated T cells from psoriasis patients." (PMID 24267790, 2013). "Additional shared signatures between ILCs and T cells were related to genes that regulate tissue residency (FOS and NR4A1; module 18) as well as quiescence (TSC22D3, DUSP1, ZFP36L2, and KLF6; module 22), the latter recently shown to be expressed by plastic skin ILCs in a mouse model of psoriasis." (PMID 37160121, 2023). "On the basis of this information, it is possible that in T cells from psoriasis patients, KLF6 up-regulation may also be induced by an UPR, in this case, triggered by the increase in protein-folding load required upon T cell activation." (PMID 24267790, 2013). "For example, cholesterol biosynthesis was the most significantly enriched process in KLF6 coexpression network and was also detected by GSEA as one of the most enriched processes in T cells from psoriasis patients." (PMID 24267790, 2013).
brain tumor (3 papers, 2007 to 2023). "KLF6 expression is elevated in ovarian malignancies, KLF8 promotes cellular proliferation in HCC, gastric, and glioma carcinomas, while KLF3 and KLF14 have been reported to inhibit tumor growth in breast and brain tumors, respectively." (PMID 37833790, 2023).
fibrosis (3 papers, 2011 to 2024). the formation of excess fibrous connective tissue in an organ or tissue in a reparative or reactive process. "In diabetic kidney tissue, miRNA-181a targets may be a Kruppel-like factor 6 (KLF6) and early growth response factor-1 (EGR-1), which are involved in the disordered proliferation of the glomerular mesangial cells, tubulointerstitial fibrosis, and enhanced cell apoptosis." (PMID 37547923, 2023). "Thus, we speculate that similar to KLF4, KLF6 may play a similar role during RSV infection of the respiratory tract since KLF6 regulates expression of TGF-β, which is involved in lung remodeling and airway fibrosis." (PMID 21849067, 2011).
Insulin resistance (3 papers, 2018 to 2023). Increased resistance towards insulin, that is, diminished effectiveness of insulin in reducing blood glucose levels. "Studies in human populations identified an association of gene polymorphism in the Klf6 gene, KLF6-IVS1–27A, that attenuates Klf6 splicing with hepatic insulin resistance and delays NAFLD progression." (PMID 36902112, 2023). "Studies in murine hepatocytes indicate that KLF6 binds to the promoter of Glucokinase (Gck) and increases its expression, leading to hepatic insulin resistance and the development of non-alcoholic fatty liver disease (NAFLD)." (PMID 36902112, 2023). "KLF6 has also been studied for its role in hepatic insulin resistance and glucose metabolism." (PMID 36902112, 2023). "Similarly, KLF6 increases PPARα activity post-transcriptionally and contributes to hepatic insulin resistance." (PMID 36902112, 2023). "PPARα controls several genes that promote insulin resistance and NASH, including Trib3, whose expression is correlated with that of KLF6 in liver tissue from humans with NAFLD." (PMID 29942807, 2018).
ischemic stroke (3 papers, 2021 to 2024). A stroke disorder caused by obstruction of blood flow to the brain, due to thrombotic (local blood clot formation) or embolic (due to a blood clot or other material traveling from another site) event. "For instance, HOTAIR-miR-148p-Kruppel-like factor 6 (KLF6) signaling cascade has been implicated induction of neuronal death following ischemic stroke." (PMID 38366205, 2024). "Subsequent immunohistochemical staining in tissues from 1-week post-ischemic stroke and control marmosets, revealed an increased number of astrocytes colocalizing NogoA and either GAP43, KLF6, or CD44, consistent with the transcriptomic results." (PMID 34824275, 2021).
leukemia (3 papers, 2013 to 2018). A malignant (clonal) hematologic disorder, involving hematopoietic stem cells and characterized by the presence of primitive or atypical myeloid or lymphoid cells in the bone marrow and the blood. "Next, we determined the effect of shRNA-mediated KLF6 knockdown on the PTTG1and CD11b expression in PMA-primed leukemia cells." (PMID 23977008, 2013). "In this study, we demonstrated that the oncogene PTTG1, which is overexpressed in leukemia cells, is transcriptionally repressed by the tumor suppressor KLF6 in response to PMA-induced myeloid differentiation." (PMID 23977008, 2013). "In addition, it is also possible that ALOX5 is required more by RE than RE9a in leukemia development, especially given that RE more strongly upregulates KLF6 expression." (PMID 24130502, 2013). "Thus, it appears that PTTG1 suppression in PMA-primed leukemia cells goes through the activation of the PKC/ERK/KLF6 pathway." (PMID 23977008, 2013). "Furthermore, KLF6 is specifically upregulated by RUNX1-ETO in human leukemia cells." (PMID 24130502, 2013).
osteosarcoma (3 papers, 2013 to 2021). A usually aggressive malignant bone-forming mesenchymal neoplasm, predominantly affecting adolescents and young adults. "Then, our current in vitro and in vivo study aimed to investigate the effect of lnc-KASRT on regulating malignant tumor behaviors and the implication of its interaction with KLF6 alternative splicing in osteosarcoma." (PMID 34568030, 2021). "The role of lnc-KASRT and KLF6 alternative splicing in osteosarcoma development and progression is unclear." (PMID 34568030, 2021). "Then, the current in vitro and in vivo study aimed to investigate the effect of lnc-KASRT on regulating tumor malignant behaviors, and the implication of its interaction with KLF6 alternative splicing in osteosarcoma." (PMID 34568030, 2021). "For instance, a study revealed that KLF6 represses cell proliferation and invasion while promoting cell apoptosis in a p21-dependent manner in osteosarcoma; furthermore, another study demonstrated that KLF6 is insufficiently expressed in osteosarcoma cells and tissues." (PMID 34568030, 2021). "Furthermore, they also confirmed that overexpression of circMTO1 could promote Kruppel like factor 6 (KLF6) expression by sponging miR-630, thereby playing a tumor suppressor role in osteosarcoma." (PMID 34277605, 2021). "Lnc-KASRT serves as a potential treatment target via regulating SRSF1-related KLF6 alternative splicing and following P21/CCND1 pathway in osteosarcoma." (PMID 34568030, 2021). "In conclusion, lnc-KASRT serves as a potential treatment target by regulating SRSF1-related KLF6 alternative splicing and the P21/CCND1 pathway in osteosarcoma." (PMID 34568030, 2021). "Therefore, our current study found that lnc-KASRT promoted osteosarcoma cell viability and mobility; moreover, lnc-KASRT regulated KLF6 alternative splicing to induce KLF6-SV1 while repressing KLF6-WT and regulating P21 and CCND1 expression in osteosarcoma." (PMID 34568030, 2021). "This visual summary shows that lnc-KASRT located on SRSF1, interacts with SRSF1, then regulates alternative splicing of KLF6 to promote KLF6-SV1 coding while inhibiting KLF6-WT coding, and subsequently modifies P21/CCND1 pathway, finally leading to increased growth and invasion of osteosarcoma." (PMID 34568030, 2021).
pulmonary fibrosis (3 papers, 2011 to 2022). Chronic progressive interstitial lung disorder characterized by the replacement of the lung tissue by connective tissue, leading to progressive dyspnea, respiratory failure, or right heart failure. "Interestingly, KLF6 is expressed in the lungs and KLF4 (both KLF4 and KLF6 are phylogenitically related since both belong to group-2 of KLF factors) expression in lung is potentially associated with pulmonary fibrosis and enhanced inflammation of the airway." (PMID 21849067, 2011). "Notably, CD4+ T cells in cluster T9 expressed high levels of KLF6 that positively regulates the expression of TGFβ and molecules in the TGFβ pathway, AREG (amphiregulin) that is involved in pulmonary fibrosis, and CXCR4 that may promote T-cell migration to the lung." (PMID 35558069, 2022).
renal carcinoma (3 papers, 2019 to 2025). A carcinoma arising from the epithelium of the renal parenchyma or the renal pelvis. "In renal carcinoma, kruppel-like factor 6 (KLF6) activates mTOR signaling and its downstream lipid metabolism regulator, SREBP-2 to enhance tumor growth." (PMID 32974183, 2020). "In renal carcinoma, CBX4 interacts with histone deacetylase 1 (HDAC1) to suppress the transcriptional activity of the Kruppel-like factor 6 (KLF6) promoter, leading to reduced KLF6 expression and tumor-promoting effects." (PMID 41502529, 2025).